NT5C1B (5'-nucleotidase, cytosolic IB)
Description:
Catalyzes the hydrolysis of nucleotide monophosphates, releasing inorganic phosphate and the corresponding nucleoside, AMP is the major substrate.
Synonyms: cN1B; cN-IB; AIRP
Tractability: Antibody: the Human Protein Atlas places it where antibodies can reach.
Gene: Protein-coding gene on chromosome 2 (18,562,871 to 18,589,572, reverse strand). Ensembl gene ENSG00000185013.
Subcellular location: Cytoplasm
Subcellular location (Human Protein Atlas): Nucleoli; Plasma membrane; Connecting piece; Mid piece; Nucleoplasm
Pathways (Reactome):
Metabolism: Purine catabolism
Gene Ontology:
Molecular function: 5'-nucleotidase activity; magnesium ion binding; nucleotide binding
Biological process: adenosine metabolic process; purine nucleotide catabolic process; AMP catabolic process; nucleotide metabolic process
Cellular component: nucleus; cytoplasm; cytosol
Genetic constraint (gnomAD): Loss-of-function variants: 44 observed, 59.37 expected, observed/expected ratio (o/e) 0.74, 90% interval 0.58 to 0.95. The upper end of that interval is the gene's LOEUF score, 0.95, which puts it in group 4 of 6, group 1 being the genes least tolerant of losing a copy. Missense variants: 742 observed, 744.09 expected, observed/expected ratio (o/e) 1, 90% interval 0.94 to 1.06. Synonymous variants: 284 observed, 287.69 expected, observed/expected ratio (o/e) 0.99, 90% interval 0.89 to 1.09.
Homologues: Orthologues: chimpanzee NT5C1B (98% identical), dog NT5C1B (81% identical), macaque NT5C1B (78% identical), rabbit NT5C1B (78% identical), mouse Nt5c1b (75% identical), rat Nt5c1b (75% identical), pig NT5C1B (74% identical), guinea pig NT5C1B (67% identical), tropical clawed frog nt5c1a (43% identical), zebrafish nt5c1bb (42% identical), zebrafish nt5c1ba (42% identical). Paralogues in human: NT5C1A (41% identical).
Diseases named in the same sentence as NT5C1B in open-access papers:
NT5C1B is named in the same sentence as 7 diseases in open-access papers, as found by Europe PMC text mining. Sharing a sentence is not in itself a finding about the gene and the disease. The quoted sentences say what the papers report.
colorectal cancer (1 paper, 2014). A primary or metastatic malignant neoplasm that affects the colon or rectum. "To do this, we selected a small sub-group of these genes that remained transcriptionally silenced in the colorectal cancer cell lines HCT116 and SW480 (ARRDC5, C4orf17, C20orf201, DDX4, NT5C1B, STRA8, TDRD12)." (PMID 25594001, 2014).
NT5C1B also shares sentences with these, for which no sentence is quoted: tumor (3 papers); breast carcinoma (1); cancer (1); colon adenocarcinoma (1); Infertility (1); papillary thyroid cancer (1).